ARID1B (AT-rich interaction domain 1B)
Description:
Involved in transcriptional activation and repression of select genes by chromatin remodeling (alteration of DNA-nucleosome topology). Component of SWI/SNF chromatin remodeling complexes that carry out key enzymatic activities, changing chromatin structure by altering DNA-histone contacts within a nucleosome in an ATP-dependent manner. Belongs to the neural progenitors-specific chromatin remodeling complex (npBAF complex) and the neuron-specific chromatin remodeling complex (nBAF complex). During neural development a switch from a stem/progenitor to a postmitotic chromatin remodeling mechanism occurs as neurons exit the cell cycle and become committed to their adult state. The transition from proliferating neural stem/progenitor cells to postmitotic neurons requires a switch in subunit composition of the npBAF and nBAF complexes. As neural progenitors exit mitosis and differentiate into neurons, npBAF complexes which contain ACTL6A/BAF53A and PHF10/BAF45A, are exchanged for homologous alternative ACTL6B/BAF53B and DPF1/BAF45B or DPF3/BAF45C subunits in neuron-specific complexes (nBAF). The npBAF complex is essential for the self-renewal/proliferative capacity of the multipotent neural stem cells. The nBAF complex along with CREST plays a role regulating the activity of genes essential for dendrite growth (By similarity). Binds DNA non-specifically.
Synonyms: BAF250B; DAN15; KIAA1235; OSA2; ELD/OSA1; p250R; 6A3-5; SMARCF2; BRIGHT; CSS1; MRD12
Tractability: Antibody: its Gene Ontology location is reachable by antibodies, with high confidence. PROTAC: ubiquitination databases record sites on it; its protein half-life has been measured.
Gene: Protein-coding gene on chromosome 6 (156,776,020 to 157,210,779, forward strand). Ensembl gene ENSG00000049618.
Subcellular location: Nucleus
Subcellular location (Human Protein Atlas): Nucleoplasm; Cytosol; Plasma membrane
Pathways (Reactome):
Chromatin organization: Formation of neuronal progenitor and neuronal BAF (npBAF and nBAF); Formation of the canonical BAF (cBAF) complex; RMTs methylate histone arginines
Gene expression (Transcription): RUNX1 interacts with co-factors whose precise effect on RUNX1 targets is not known; Regulation of endogenous retroelements by Piwi-interacting RNAs (piRNAs)
Developmental Biology: Regulation of MITF-M-dependent genes involved in pigmentation
Gene Ontology:
Molecular function: DNA binding; protein binding; nucleosome binding; transcription coactivator activity
Biological process: chromatin remodeling; positive regulation of cell differentiation; positive regulation of DNA-templated transcription; positive regulation of double-strand break repair; positive regulation of myoblast differentiation; positive regulation of T cell differentiation; regulation of G0 to G1 transition; regulation of G1/S transition of mitotic cell cycle; regulation of mitotic metaphase/anaphase transition; regulation of nucleotide-excision repair; regulation of transcription by RNA polymerase II; transcription initiation-coupled chromatin remodeling
Cellular component: nucleoplasm; nucleus; SWI/SNF complex; bBAF complex; brahma complex; chromatin; nBAF complex; npBAF complex
Genetic constraint (gnomAD): Loss-of-function variants: 29 observed, 192.54 expected, observed/expected ratio (o/e) 0.15, 90% interval 0.11 to 0.2. The synonymous counts are far from expectation, so gnomAD's model fits this gene poorly and the ratio says little. Missense variants: 2,856 observed, 2,977.1 expected, observed/expected ratio (o/e) 0.96, 90% interval 0.93 to 0.99. Synonymous variants: 1,385 observed, 1,198.3 expected, observed/expected ratio (o/e) 1.16, 90% interval 1.11 to 1.21.
Gene-disease validity (ClinGen):
ClinGen rates the evidence that ARID1B causes each of these diseases.
Coffin-Siris syndrome (autosomal dominant): Definitive. Coffin-Siris syndrome (CSS) is a rare congenital multi-systemic genetic disorder characterized by aplasia or hypoplasia of the distal phalanx or nail of the fifth digit, developmental delay, intellectual disability, coarse facial features, and other variable clinical manifestations.
Cancer hallmarks: genome instability and mutations (suppresses); suppression of growth (promotes); proliferative signalling (promotes); invasion and metastasis (promotes)
Homologues: Orthologues: macaque ARID1B (99% identical), chimpanzee ARID1B (98% identical), pig ARID1B (95% identical), dog ARID1B (93% identical), rat Arid1b (92% identical), mouse Arid1b (90% identical), tropical clawed frog arid1b (70% identical), rabbit ARID1B (63% identical), guinea pig ARID1B (63% identical), zebrafish arid1b (51% identical), Drosophila melanogaster osa (27% identical), Caenorhabditis elegans let-526 (19% identical). Paralogues in human: ARID1A (49% identical).
Diseases named in the same sentence as ARID1B in open-access papers:
ARID1B is named in the same sentence as 191 diseases in open-access papers, as found by Europe PMC text mining. Sharing a sentence is not in itself a finding about the gene and the disease. The quoted sentences say what the papers report.
Coffin-Siris syndrome (73 papers, 2012 to 2026). "We detected variants related to eight genes in nine patients (9/10, 90.0%), where we identified three variants in the ARID1B gene and confirmed two cases of Coffin–Siris syndrome as well as one case of Rubinstein–Taybi syndrome." (PMID 38933926, 2024). "We here perform saturated mutagenesis screens on ARID1B and demonstrate that protein destabilization is the main mechanism associated with pathogenic missense mutations in patients with Coffin–Siris Syndrome." (PMID 38347147, 2024). "Other examples highlighted by our analysis include 2 large genes, ARID1B (associated with Coffin-Siris syndrome, MIM #135900) and NSD1 (associated with Sotos syndrome, MIM #117550), which have 13 and 31 pLoFs in UKB, respectively." (PMID 38671509, 2024). "The second most common occurrence was observed for ARID1B, one of the genes underlying Coffin-Siris syndrome." (PMID 38395944, 2024). "ARID1B haploinsufficiency in humans causes Coffin-Siris syndrome, associated with developmental delay, facial dysmorphism, and intellectual disability." (PMID 38816354, 2024). "Genetic testing revealed a heterozygous de novo pathogenic variant (class 5) c.1638_1647del in the ARID1B gene that is causative of Coffin-Siris syndrome but also other intellectual disability (ID)-related disorders, including autism." (PMID 37692302, 2023). "ARID1B (AT-rich interactive domain-containing protein 1B [MIM *614556]) is recognized as the most common causative gene for Coffin-Siris syndrome (CSS; MIM #135900), which is inherited in an autosomal dominant manner." (PMID 35879281, 2022). "Mental retardation and language delay were observed after birth, which was consistent with the phenotype of Coffin-Siris syndrome mainly caused by mutations of ARID1B." (PMID 34980134, 2022). "De novo ARID1B haploinsufficient mutations cause neurodevelopmental disorders, including Coffin-Siris syndrome, which is characterized by neurological and craniofacial features." (PMID 34753942, 2021). "Often, ARID1B mutations result in Coffin-Siris Syndrome, a relatively rare genetic disorder that manifests at birth and is characterized by both intellectual disabilities and physical phenotypes." (PMID 33748136, 2021). "Haploinsufficiency of the epigenetic regulator ARID1B, which we previously discussed as the causal gene for Coffin-Siris Syndrome, was found to cause premature apoptosis in MGE precursors in mice." (PMID 33263776, 2021). "Mutations were detected in four of them: one with a mutation in the ARID1B gene (Coffin–Siris syndrome), one with a microdeletion (Xq28), one with a non‐relevant heterozygous mutation in the DISP1 gene and one with a DCC mutation." (PMID 32484578, 2021). "Mutations in the ARID1B subunit of the BAF chromatin remodeling complex are associated with the neurodevelopmental Coffin-Siris syndrome." (PMID 34753942, 2021). "To date, nine genes have been reported to be related to Coffin-Siris syndrome, and mutations of ARID1B gene were the most common reason for Coffin-Siris syndrome." (PMID 34858471, 2021). "Mutations in ARID1B cause Coffin-Siris syndrome (CSS), which is a rare hereditary disorder affecting multiple body systems, for instance the nervous, cardiovascular, and skeletal systems." (PMID 31323019, 2019). "Participant 1 (P1) presents a de novo duplication-inversion-inversion-deletion encompassing ARID1B (MIM: 135900) that causes Coffin-Siris syndrome (CSS [MIM: 135900])." (PMID 30526634, 2018). "Patients with Coffin-Siris syndrome, which is associated with the ARID1B mutation, also have short stature." (PMID 28867767, 2017). "Some doctors are already treating people with Coffin-Siris syndrome with growth hormone, and these new findings suggest that this treatment counteracts defects caused directly by the mutation affecting ARID1B." (PMID 28695822, 2017).
Coffin-Siris syndrome (continued). "ARID1B has been identified as one of the causal genes for Coffin-Siris syndrome and it has also been associated with syndromic intellectual disability." (PMID 26376624, 2015). "A following retrospective genotype-phenotype analysis based on a literature review confirmed that short stature is a frequent feature in those Coffin-Siris syndrome patients with ARID1B mutations." (PMID 26376624, 2015). "An analogous observation is the presence of microcephaly in a minority of patients with ARID1B mutations and more broadly in Coffin-Siris syndrome." (PMID 24674232, 2014). "In humans, haploinsufficiency of ARID1B is associated with neurodevelopmental disorders and syndromic/non-syndromic intellectual disabilities, including Coffin-Siris syndrome and HHID syndrome, and ARID1B mutations have been identified in different human cancers." (PMID 38816354, 2024). "Heterozygous ARID1B variants result in Coffin-Siris syndrome." (PMID 37654076, 2023). "ARID1B was among the genes in this Coffin Siris syndrome-associated gene list." (PMID 34645894, 2021). "Additionally, ARID1B has been associated with multiple syndromes characterized by developmental delay and intellectual disability, such as Coffin-Siris syndrome, and with non-syndromic intellectual disability." (PMID 32380822, 2021). "This region contains the ARID1B gene, whose mutation is responsible for Coffin-Siris syndrome." (PMID 33584783, 2020). "This gene is associated with Coffin-Siris syndrome (ARID1B)." (PMID 30510536, 2018). "Mutations that affect one component of this complex, a protein known ARID1B, are associated with a rare genetic condition called Coffin-Siris syndrome, and may also have a role to play in autism spectrum disorders and intellectual disability." (PMID 28695822, 2017). "In addition to autistic patients, mutations in the ARID1B gene are observed in patients with neurodevelopmental delay, intellectual disability, growth delay, and Coffin-Siris syndrome." (PMID 28867767, 2017). "ARID1B is associated with the Coffin-Siris syndrome, and the clinical features of the patient 2 are compatible with this diagnosis (mainly the neonatal eating disorders, ID, motor and speech delay, hypertrichosis, synophrys, dystrophic toenails, clinodactyly, and short fingers)." (PMID 28630856, 2017). "ARID1B, a causal gene for Coffin Siris syndrome, is the only gene encompassed by all three CNVs." (PMID 26376624, 2015). "Thus, growth retardation and short stature is a common feature associated with mutations in ARID1B and Coffin-Siris syndrome." (PMID 26376624, 2015). "A total of 70 patients with mutations in ARID1B (including translocation, deletion, duplication, nonsense and truncating mutations) have been described in the literature and Decipher database, many of whom have Coffin-Siris syndrome." (PMID 26376624, 2015). "This study broadens the spectrum of ARID1B associated phenotypes by describing a distinctive phenotype including plantar fat pads but lacking the hypertrichosis or fifth nail hypoplasia associated with Coffin-Siris syndrome." (PMID 24674232, 2014). "Mutations in ARID1A and ARID1B are also an important cause of Coffin-Siris Syndrome (CSS; OMIM 135900), a rare autosomal-dominant neurodevelopmental syndrome." (PMID 35615272, 2022). "Therefore, we speculate that the dysregulation of neuroectoderm specification caused by ARID1B mutations may underlie both the cognitive impairment and craniofacial abnormalities that are typical of Coffin-Siris syndrome." (PMID 34753942, 2021). "ARID1B is the most commonly mutated gene in Coffin-Siris syndrome (CSS), a monogenic syndrome characterized by growth retardation, facial dysmorphism, and intellectual disability (ID)." (PMID 28695822, 2017). "The phenotype is not clinically recognizable, except in those who harbor a terminal 6q deletion that includes the ARID1B gene, in whom features similar to Coffin–Siris syndrome (CSS) can be observed." (PMID 41300817, 2025).
Coffin-Siris syndrome (continued). "These potentially targetable disorders include NDDs like Coffin-Siris syndrome (ARID1B; OMIM: 105830), Kleefstra syndrome (EHMT1; OMIM:610253), and Koolen-De Vries syndrome (KANSL1; OMIM: 610443)." (PMID 40400017, 2025). "ARID1B typically shows high penetrance but with a broad phenotypic spectrum, ranging from severe disorders such as Coffin–Siris syndrome to milder or subclinical presentations consistent with BAP traits." (PMID 40731902, 2025). "ARID1B is the most frequently mutated gene in Coffin-Siris syndrome (CSS)." (PMID 39028335, 2024). "Using deep mutational scanning, the authors uncover the functional consequence of missense mutations in ARID1B, a subunit of the SWI/SNF chromatin remodeling complex that is frequently mutated in human Coffin–Siris syndrome and in cancer." (PMID 38347147, 2024). "Coffin–Siris syndrome is also called “BAFopathy” because its causal genes encode chromatin modeling BAF complex components (e.g., ARID1B and SMARCB1)." (PMID 38094004, 2023). "The current EpiSignTM BAFopathy episignature encompasses several subtypes of Coffin–Siris syndrome associated with multiple genes (ARID1A, ARID1B, SMARCB1, SMARCA4) and Nicolaides–Baraitser syndrome (SMARCA2)." (PMID 36430143, 2022). "The heterozygous Arid1b knockout mouse model of Coffin-Siris syndrome, a syndromic ID, exhibits body weight and growth rate deficits, reduced total brain volume but hippocampal enlargement, and deficits in novel object recognition." (PMID 35227461, 2022). "These include Coffin-Siris syndrome (ARID1B), Koolen-de Vries syndrome (KANSL1), Kabuki syndrome (WDR5), and Kleefstra syndrome (WDR5)." (PMID 36743289, 2022). "The GeneReviews for Coffin-Siris syndrome (CSS), of which ~37% of cases are due to ARID1B variants, reports that fewer than 200 individuals with CSS have been identified, although a literature and social media review suggests that this number is higher." (PMID 36359385, 2022). "ARID1B deficiency in the brain leads to ASD, ID, and some syndromic developmental disorders such as Coffin-Siris syndrome." (PMID 36743289, 2022). "PTPN11 (Noonan syndrome 1, OMIM 163950) and ARID1B (Coffin-Siris syndrome 1, OMIM 135900) were recurrently reported in 11 patients and 10 patients, respectively." (PMID 35346031, 2022). "Lastly, a mouse model for Arid1b and Smarcb1 deficits (Coffin-Siris Syndrome) indeed mirror the human phenotype, as Arid1b+/− and Smarcb1+/inv NesCre+/− mice also have a significantly reduced corpus callosum thickness." (PMID 33263776, 2021). "De novo disruptions to ARID1B (AT-rich interaction domain 1B) are associated with ASD, Coffin-Siris syndrome, agenesis of the corpus callosum, and short stature, possibly mediated by dysregulation of the Wnt/β-catenin pathway." (PMID 34148555, 2021). "Two patients (cases 21 and 22) with skeletal manifestations such as scoliosis and kyphosis and moderate developmental delay were diagnosed with ARID1B-related Coffin-Siris syndrome." (PMID 34122524, 2021). "Interestingly, ARID1B is associated with joint laxity via a multisystemic Coffin-Siris syndrome (CSS); CSS is caused by ARID1B variants and 66% of the CSS patients exhibit joint laxity." (PMID 31881848, 2019). "Later published studies discovered the etiology of the phenotypically related Coffin-Siris syndrome to be caused by similar mutations in SMARCB1 and ARID1B, which are direct interaction partners of SMARCA2 in the SWI/SNF chromatin remodeling complex." (PMID 23013645, 2012). "Coffin–Siris syndrome presents with developmental delay and coarse facial features, but is differentiated by the absence or hypoplasia of the fifth fingernails or toenails and involvement of the ARID1B gene." (PMID 40843254, 2025).
Coffin-Siris syndrome (continued). "For instance, the SMARCB1, SMARCA4, SMARCE1, ARID1A, and ARID1B genes encode subunits of the BAF complex (also known as the SWI/SNF complex in yeast), and they are responsible for 55–70% of Coffin–Siris syndrome cases, where microcephaly can manifest as one of the phenotypes." (PMID 38094004, 2023). "To investigate the function of ARID1B in craniofacial development, we obtained skin fibroblasts from two unrelated ARID1B+/− Coffin-Siris Syndrome patients (hereafter, Patient 19 and Patient 26), one male and one female, both carrying previously identified de novo ARID1B mutations." (PMID 34753942, 2021). "ARID1B (Coffin–Siris syndrome and ASD) mediates NHEJ in cancer cells." (PMID 32737294, 2020). "In human, deleterious variations in ARID1B are thought to contribute to Coffin-Siris syndrome." (PMID 32475352, 2020). "All four patients carrying ARID1B mutation showed no signs of Coffin-Siris syndrome, or developmental or mental deficits." (PMID 26376624, 2015). "ARID1B mutations have been identified as the predominant cause of Coffin-Siris syndrome and have also been shown to be a frequent cause of nonsyndromic intellectual disability." (PMID 24674232, 2014). "Moreover, this mouse model will allow the role of ARID1B to be investigated further in the laboratory, and could be used as a tool to discover, develop and test new treatments for Coffin-Siris syndrome." (PMID 28695822, 2017). "Recently, primary (open-angle) glaucoma was described in two children with the most common form of Coffin-Siris syndrome, CSS1 (OMIM #135900) by ARID1B (AT-rich interaction domain-containing protein 1B) gene mutation." (PMID 33430815, 2021). "Sequence variants in other BAF complex genes are associated with other neurodevelopmental disorders including SMARCC1/2, PBRM1, ARID1A/B and SMARCA4 in ASD, PBRM1 and ARID1B in schizophrenia, SMARCB1 in Kleefstra syndrome, and ARID1A/B, SMARCA4, SMARCB1, and SMARCE1 Coffin-Siris syndrome (CSS)." (PMID 31288860, 2019). "Mutations in ARID1B and several other genes encoding components of the Brahma-associated factor (BAF, also referred to as switching defective and sucrose nonfermenting SWI/SNF-α) chromatin remodeling complex, were recently shown to cause Coffin-Siris syndrome (CSS)." (PMID 24674232, 2014). "Mutations in 4 different SWI/SNF subunits including ARID1A/B were identified in three congenital syndromes that include both neural and cardiac defects: Coffin-Siris syndrome (CSS), Nicolaides-Baraitser syndrome (NCBRS), and ARID1B-related intellectual disability (ID) syndrome." (PMID 32646524, 2020).